KRAS (KRas proto-oncogene, GTPase)
Diseases named in the same sentence as KRAS in open-access papers (continued):
Sharing a sentence is not in itself a finding about the gene and the disease.
cardiac hypertrophy (4 papers, 2017 to 2022). "These are both effectors of cardiac hypertrophy through their inhibition of Ras GTPase superfamily members (RASH, RASN, and KRAS)." (PMID 28649439, 2017).
epidermal nevus (4 papers, 2015 to 2022). "The identification of codon 146 KRAS variants in isolated epidermal nevus introduces a new hot spot for this condition, which is useful for increasing molecular genetic testing using targeted gene sequencing panels." (PMID 35409398, 2022). "In addition to representing known oncogenic mutations, mosaic variants in KRAS have been described in multiple conditions, including epidermal nevus, nevus sebaceous and Schimmelpenning syndrome, encephalocraniocutaneous lipomatosis, and phacomatosis pigmentokeratotica." (PMID 35740480, 2022).
genitourinary cancers (4 papers, 2017 to 2023). "There are several KRAS markers in mutated cancers, such as pancreatic, colorectal, lung, and genitourinary cancers." (PMID 36164371, 2022).
hepatoblastoma (4 papers, 2019 to 2025). Hepatoblastoma (HB) is a malignant hepatic tumor and is the most common pediatric liver cancer. "In this study, we analyzed the association between NRAS and KRAS polymorphisms and hepatoblastoma risk." (PMID 31086727, 2019). "We find that NRAS and KRAS polymorphisms are irrelevant to hepatoblastoma susceptibility among Chinese population." (PMID 31086727, 2019). "The data suggest that NRAS and KRAS polymorphisms are irrelevant to hepatoblastoma susceptibility among Chinese population." (PMID 31086727, 2019). "These issues should be avoided as much as possible in future studies to better investigate the relationship between hepatoblastoma risk and NRAS and KRAS polymorphisms." (PMID 31086727, 2019).
Hyperinsulinemia (4 papers, 2019 to 2025). An increased concentration of insulin in the blood. "In particular, visceral obesity, a high-fat diet, T2DM, IGF release and hyperinsulinemia are associated with pancreatic duct cell proliferation, pancreatic stellate cell activation, TGF-β1 release, pancreatic fibrosis and KRAS activation." (PMID 37047163, 2023). "The authors also confirmed that in acinar cells with a KRAS mutation, INSR is essential under conditions of high-fat diet-induced obesity for the hyperinsulinemia-driven formation of PanINs; INSR knockout can inhibit PDAC development associated with hyperinsulinemia." (PMID 38982491, 2024).
hyperplasia (4 papers, 2012 to 2018). An abnormal increase in the number of cells in an organ or a tissue with consequent enlargement. "This would also explain the strong upregulation that could be detected among hyperplastic polyps upon KRAS mutation, since these non-adenomatous lesions lack a “background” of Abi1 expression." (PMID 22808230, 2012).
Immunodeficiency (4 papers, 2020 to 2024). Failure of the immune system to protect the body adequately from infection, due to the absence or insufficiency of some component process or substance. "KRAS mutations in Cluster 2 involved changes in pathways such as taurine and hypotaurine metabolism, immunodeficiency, antigen processing and presentation." (PMID 35340619, 2022). "There were differences in multiple pathways between patients in the KRAS gene mutation group and patients in the nonmutation group, including immunodeficiency, natural killer cell-mediated cytotoxicity, JAK stat signaling pathway, etc.." (PMID 35340619, 2022).
Intellectual disability (4 papers, 2020 to 2024). "MAP2K1 variants are correlated with skeletal deformities and motor dysfunction, and MAP2K2 and KRAS variants are correlated with mild intellectual disability." (PMID 37697378, 2023). "KRAS mutations are associated with rare cases of neurodevelopmental disorders that can cause intellectual disabilities." (PMID 33082413, 2020). "There are indications that intellectual disabilities are more frequent and more severe in patients with KRAS." (PMID 36012976, 2022). "Intellectual disability is reported to be more common in CFCS, which is associated with variants in BRAF (~75% of the CFCS cases), MAP2K1 and MAP2K2 (~25%), and KRAS (<2–3%)." (PMID 36012976, 2022).
Langerhans cell histiocytosis (4 papers, 2022 to 2024). Langerhans cell histiocytosis (LCH) is a systemic disease associated with the proliferation and accumulation (usually in granulomas) of Langerhans cells in various tissues. "KRAS-positive genomic analysis favors a diagnosis of histiocytoma, while the solitary calvarium and spontaneous resolution with remission favor a diagnosis of Langerhans cell histiocytosis (LHC)." (PMID 38529420, 2024). "ECD is often found alongside Langerhans cell histiocytosis (LCH), which is characterized by mutations in the MAPK/ERK pathway, including KRAS gene." (PMID 39724464, 2024). "PCR results showed that there were no BRAF-V600E, KRAS, or NRAS mutations in primary intraosseous RDD; only one case with both RDD and Langerhans cell histiocytosis showed BRAF-V600E mutation." (PMID 36185213, 2022).
laryngeal squamous cell carcinoma (4 papers, 2021 to 2024). A squamous cell carcinoma that arises from the larynx. "It has also been found that KRAS overexpression was associated with the progressive dedifferentiation of laryngeal squamous cell carcinoma." (PMID 38228050, 2023). "SNPs in the 3'UTR region of NRAS and KRAS genes can play an important role in the progression of cancers including laryngeal squamous cell carcinoma by affecting gene expression and RNA regulatory interactions." (PMID 39867023, 2024).
liver angiosarcoma (4 papers, 2009 to 2025). A malignant vascular neoplasm arising from the liver.
liver cirrhosis (4 papers, 2016 to 2023). "The minimum width of rim fluorescence surrounding tumors is negatively associated with the tumor type, tumor size, liver cirrhosis, neoadjuvant chemotherapy, and KRAS and BRAF mutation (all P > 0.05)." (PMID 36484905, 2023). "Both HCC and PDAC develop through multiple stages, and these stages are associated with specific mutations e.g., KRAS as an early mutation that occurs in PanIN, and TERT promoter methylation that occurs following liver cirrhosis." (PMID 31608239, 2019).
lupus (4 papers, 2022 to 2025). "We hereby report a refractory SLE case with monocytosis accompanying somatic KRAS mutation that have been shown to cause lupus-like symptoms." (PMID 35361277, 2022). "Lupus-like symptoms with monocytosis reminded us of Ras-associated autoimmune leukoproliferative disorder, and Sanger sequencing of KRAS and NRAS genes from the patients’ peripheral blood mononuclear cells (PBMC), sorted CD3+ lymphocytes and CD14+ monocytes, and cerebrospinal fluid were performed." (PMID 35361277, 2022). "Although two loci of KRAS have been reported, they were not related to lupus." (PMID 38970732, 2024).
medullary carcinoma (4 papers, 2017 to 2025). "Medullary carcinoma is more frequently associated with a high level of microsatellite instability, which may predict better responses to immunotherapy, and often with the wild-type KRAS gene." (PMID 36231030, 2022). "Tiles with high MSI relevance displayed medullary carcinoma patterns, including tumor cell sheets and high TILs, which corresponded to low KRAS MUT prediction scores." (PMID 39973981, 2025). "Mutations occur in any of the RAS genes (NRAS > HRAS > KRAS in nodules/tumors of follicular cells, HRAS > KRAS > NRAS in medullary carcinoma)." (PMID 38108848, 2024).
mucosal melanoma (4 papers, 2019 to 2024). A melanoma that arises from a mucosal site. "Major driver mutations in mucosal melanoma were detected in NRAS, KRAS, NF1, PTEN, GNAQ, and KIT." (PMID 39564955, 2024). "When the mucosal melanoma is triple (BRAF, NRAS, NF1)-negative, KIT is the most commonly mutated gene in vulvovaginal melanomas, while APC and KRAS are detected mainly in sinonasal and anorectal melanomas, respectively." (PMID 34571863, 2021).
myelofibrosis (4 papers, 2022 to 2024). A partial or complete replacement of the bone marrow stroma by fibrous tissue. "Myelofibrosis MSCs were transcriptionally distinct, with significant enrichment of genes and pathways associated with myofibroblast transition including Acta2, KRAS and phosphoinositide-3-kinase (PI3K) signaling, inflammatory response genes and IL2-STAT5 signaling." (PMID 39383242, 2024). "Concerning the prognostic impact of RAS mutations, in a recent study that included 723 patients with PMF and post-PV or post-ET myelofibrosis (MF), oncogenic NRAS/KRAS mutations conferred a high risk of developing sAML, leading to reduced survival." (PMID 37841434, 2023).
Nephropathy (4 papers, 2019 to 2025). A nonspecific term referring to disease or damage of the kidneys. "Renal diseases were found in 8 (16%) patients with KRAS mutations." (PMID 41438146, 2025). "Also, renal diseases were only observed in patients with KRAS mutations, while the development of skeletal abnormalities was significantly associated with mutations in the HRAS gene." (PMID 41438146, 2025). "An asymptomatic 70-year-old participant with a history of moderate to severe renal disease, tested positive on the baseline and confirmatory CancerSEEK tests based on a substitution in the KRAS gene, NM_004985.5(KRAS):c.35G>A (p.Gly12Asp)." (PMID 39512764, 2024). "In conclusion, hormone-resistant nephropathy was identified by two key genes, IL2RA and KIAA0101, and the signaling pathways involved were the KRAS signaling pathway and the mTORC1 signaling pathway." (PMID 36164371, 2022).
neurofibroma (4 papers, 2021 to 2025). An intraneural or extraneural neoplasm arising from nerve tissues and neural sheaths. "We review the previous literature of two cases of congenital skin lesions and neurofibromas and spinal nerve root hypertrophy caused by KRAS variants and highlight this presentation as an important differential diagnosis for neurofibromatosis." (PMID 40682439, 2025).
neurofibromatosis type 1 (4 papers, 2011 to 2022). A clinically heterogeneous, neurocutaneous genetic disorder characterized by cafe-au-lait spots, iris Lisch nodules, axillary and inguinal freckling, and multiple neurofibromas. "Seven genes (PTPN11, SOS1,KRAS, RAF1, BRAF,SHOC2 and MEK1, alias MAP2K1) have beencausally related to NS and closely related conditions (including LEOPARDsyndrome) and clinically related disorders (e.g. neurofibromatosis type 1)." (PMID 21526175, 2011).
oligodendroglioma (4 papers, 2019 to 2023). A well-differentiated (WHO grade II), diffusely infiltrating neuroglial tumor, typically located in the cerebral hemispheres.
pancreatic acinar cell carcinoma (4 papers, 2020 to 2024). An adenocarcinoma arising from the pancreas. "A subsequent study of 18 cats with pancreatic acinar cell carcinoma found no KRAS mutations in either codon 12 or 13, similar to that seen in pancreatic acinar cell carcinoma in humans." (PMID 36288160, 2022). "Another patient with an absent mutation calling in KRAS, as observed by the “water-burst” dPCR assay, was pathologically diagnosed as having a pancreatic acinar cell carcinoma with no KRAS mutations (patient 7)." (PMID 32704002, 2020). "In patient 7, who was diagnosed with a pancreatic acinar cell carcinoma exhibiting no KRAS mutations, the level of the KRAS G12/G13 variant was found to be approximately similar to the detection limit of the screening kit (0.2%)." (PMID 32704002, 2020).
paraganglioma (4 papers, 2017 to 2025). A benign or malignant neoplasm arising from paraganglia located along the sympathetic or parasympathetic nerves. "The KRAS pathway was found togenerally display a broader distribution and lower PAL values (except inpheochromocytoma and paraganglioma, where its median value is higher) comparedto the ERK1/2 pathways." (PMID 40264578, 2025).
penile cancer (4 papers, 2013 to 2016). A primary or metastatic malignant neoplasm that affects the penis. "From a biological perspective, EGFR appears a promising target in penile cancer, as it is universally expressed and frequently phosphorylated, but infrequently amplified, or mutated, while mutations of downstream signaling proteins (such as KRAS/BRAF) are rare." (PMID 28066240, 2016). "A recent report showed a dysregulation of phosphatidylinositol 3-kinase and Ras pathways through somatic alterations of the PIK3CA, HRAS and KRAS genes in 11 out of 28 (39%) penile cancer samples, without any statistically significant difference between HPV-positive and HPV-negative cases." (PMID 23305393, 2013).
peritoneal cancer (4 papers, 2021 to 2026). A peritoneum cancer that is located in the inside of the abdomen. "It takes into account peritoneal cancer index, nodal status, differentiation grading, and KRAS/BRAF mutations and allows categorization of patients into 4 survival groups with a prediction performance of 0.70 (development/validation area under the curve)." (PMID 36077810, 2022). "Variables included peritoneal cancer index (PCI), tumor location, histology, HIPEC regimen, and KRAS/BRAF/SMAD4 status." (PMID 41595218, 2026). "CRS-HIPEC suitability is based on peritoneal cancer index (PCI), histologic subtype, KRAS status, and performance status." (PMID 40724549, 2025). "Within the categories into which the peritoneal cancer index (PCI) was classified, survival at 36 months depended on the KRAS status." (PMID 34557315, 2021).
peritoneal disease (4 papers, 2015 to 2024). "Survival was significantly associated with the grade of the primary neoplasm, the grade of the peritoneal disease, the completeness of cytoreduction score and with mutation in either GNAS, KRAS or both." (PMID 39435876, 2024). "Comparing mouse, spleen, and tumor masses, we observed STOSE and MOE-PTEN/KRAS cells tended to generate larger orthotopic tumors, while ID8-derived models generated more extensive peritoneal disease and ID8-WT mice had higher ascites accumulation." (PMID 36311166, 2022).
plasma cell dyscrasia (4 papers, 2009 to 2023). "From a cohort of 217 patients with plasma cell neoplasm that underwent NGS mutation profiling, we identified 68 (31.3%) patients who had mutations in RAS signaling pathway genes (KRAS, NRAS or BRAF) and no other mutations." (PMID 37212518, 2023).
polyposis (4 papers, 2006 to 2026). "For instance, G>T transversions in position c.34 of a KRAS gene serves as a pre-screening tool for MUTYH-associated polyposis diagnosis." (PMID 35628513, 2022). "Approximately 11% of the patients with KRAS‐G12C mutations carried at least one germline pathogenic variant in MUTYH, with 6.8% of these patients being biallelic and diagnosed with MUTYH‐associated polyposis." (PMID 41347765, 2026). "In summary, our findings reveal an increased prevalence of biallelic MUTYH carriers among CRC patients with the KRAS‐G12C somatic mutation, underscoring that its detection should prompt MUTYH genetic testing, even in the absence of a family history of CRC or a polyposis condition." (PMID 41347765, 2026).
Reovirus infection (4 papers, 2014 to 2020). "This study warrants the necessity to delineate at the molecular level the mechanism adopted by TLR3 in reovirus infection and propagation with special emphasis on KRAS mutated CRC condition as a progress towards search of a better therapy of KRAS mutated CRC." (PMID 28422714, 2017). "Reovirus infection induced a significantly higher percentage of TUNEL positive cells in KRAS mutant HCT116 cells with 12.22 ±0.24% (mean ± SEM) apoptotic TUNEL positive cells compared to Hke3 cells 4.66 ± 0.345% (mean ±SEM)." (PMID 24798549, 2014). "We next performed western blot analysis to explore the molecular events that drive the enhanced apoptosis of KRAS mutant HCT116 cells following reovirus infection." (PMID 24798549, 2014). "The study further showed that reovirus infection induces mutant KRAS activity within the CRC cells." (PMID 33426543, 2020). "Reovirus infection at a MOI of 2 for 72 hours induced significantly higher release of LDH in KRAS mutant HCT116 cells (39.27 ± 2.9%) compared to KRAS WT Hke3 cells (20.64 ± 5.2%; p=0.0057), indicating greater disruption of membrane integrity in KRAS mutant HCT116 cells." (PMID 24798549, 2014). "Mutant KRAS was induced by treatment with 5 mM IPTG for 72h prior to reovirus infection." (PMID 24798549, 2014). "In absence of reovirus infection such induction of KRAS activity in CRC cells would indicate rapid proliferation and subsequent progression of cancer." (PMID 33426543, 2020).
salivary gland tumors (4 papers, 2015 to 2023). "KRAS mutations are rare in salivary gland tumors and have been mainly detected sporadically in rare malignant neoplasms." (PMID 36752878, 2023). "In one worldwide meta-analysis study, the overall frequency of KRAS mutations in salivary gland tumors was 0.98% compared to a higher (10%) frequency of HRAS mutations." (PMID 36752878, 2023). "PIK3CA mutations were found in 59% of HRAS-mutant salivary gland tumors but due to the limited number of KRAS- and NRAS-mutant tumors of this lineage this was not significantly different, but was more prevalent than in other HRAS-mutant cancers (p<0.05)." (PMID 37503077, 2023).